CXCL5 (C-X-C motif chemokine ligand 5)
Diseases named in the same sentence as CXCL5 in open-access papers (continued):
Sharing a sentence is not in itself a finding about the gene and the disease.
lung cancer (continued). "Data from several sources have identified the involvement of CXCL5 in the proliferation of other types of tumor cells, such as prostate cancer, lung cancer, cervical cancer, hepatoblastoma, osteosarcoma, and papillary thyroid carcinoma." (PMID 35702353, 2022). "For example, in a mouse lung cancer model, CXCL5 antibodies synergistically enhanced the therapeutic effect of the tyrosine kinase inhibitor gefitinib through activating the AKT/NF‐κB and ERK/RSK1/2 signaling pathways." (PMID 35702353, 2022). "We employed mouse Lewis lung carcinoma cell line and human lung cancer cell line H460, which expressed CXCR2 on the surface and secreted CXCR2-associated chemokines, such as CXCL1, CXCL2, CXCL5 and MIF." (PMID 33814009, 2021). "There was an inverse correlation between DACH1 mRNA levels and CXCL5 in both lung cancer cell lines and human NSCLC tissues." (PMID 25788272, 2015). "To further explore the functional relationship between DACH1 and CXCL5, we searched lung cancer cell lines and tumor tissues database for mRNA expression." (PMID 25788272, 2015). "In this study, we examined the production of pro-angiogenic factors, VEGF, IL-8/CXCL8, and CXCL5, to determine the effects of IL-27 on angiogenesis in human lung cancer." (PMID 24274066, 2013). "In addition, we investigated the influence of CXCL5 on the survival of patients with lung cancer, which revealed a positive correlation between CXCL5 levels and poor prognosis." (PMID 39034411, 2024). "CXCL5 may serve as a potential therapeutic target in synergy with ICBs in lung cancer immunotherapy." (PMID 39034411, 2024). "In this study, we found that autocrine CXCL5 by lung cancer improves its PD-L1 expression." (PMID 39034411, 2024). "However, the biological implications of CXCL5 in regulating PD-1/PD-L1 signaling and antitumor immunity in lung cancer remain largely unclear." (PMID 39034411, 2024). "CXCL5 may serve as a potential therapeutic target in synergy with existed ICBs in lung cancer immunotherapy." (PMID 39034411, 2024). "Given that neutrophils express CXCR2, we hypothesized that lung cancer-secreted CXCL5 may attract neutrophils in peripheral blood mononuclear cells (PBMCs) to enter the TME." (PMID 39034411, 2024). "Our findings collectively demonstrate that CXCL5 overexpression promotes immune escape and predicts a poor outcome in patients with lung cancer, indicating that CXCL5 may serve as a potential therapeutic target that could synergize with ICBs." (PMID 39034411, 2024). "In addition, combined utilization of anti-CXCL5 and anti-PD-L1 yielded the most effective outcome in controlling lung cancer, with convinced biological safety." (PMID 39034411, 2024). "In lung cancer, Schwann cells secreted-CXCL5 is responsible for metastasis by inducing EMT31." (PMID 32632106, 2020). "CXCL5 can promote the proliferation and metastasis of lung cancer cells." (PMID 30718976, 2019). "Importantly, there was an inverse relationship between the expression of DACH1 and CXCL5 in human lung cancer cell lines and NSCLC tissues." (PMID 25788272, 2015). "In addition, paracrine CXCL5 attracts neutrophils into the lung cancer microenvironment." (PMID 39034411, 2024). "Moreover, CXCL5 was measured in NC and PD-L1 KD lung cancer cells through ELISA and IF." (PMID 39034411, 2024). "A previous study showed that Schwann cells-derived CXCL5 promotes EMT, invasiveness, and metastasis of lung cancer cells." (PMID 40052442, 2025). "Schwann cells, through secreting C-X-C motif chemokine ligand 5 (CXCL5), activate the PI3K/AKT/GSK-3β/Snail-Twist signaling pathway in lung cancer cells, mediates EMT, and increases the motility, invasiveness, and metastatic potential of lung cancer cells." (PMID 39981185, 2025). "For lung cancer, bioinformatic analysis of the transcriptome of SCs demonstrated the secretion of high levels of CCL2, CXCL5, CXCL12, and CXCL8, and functional data suggested that CCL2 promoted the M2 polarization of macrophages." (PMID 38638689, 2024).
lung cancer (continued). "In this study, we demonstrated that tumor-secreted CXCL5 induces phosphorylation of the PXN/AKT pathway, leading to PD-L1 upregulation in lung cancer and enabling the evasion of immune surveillance by CD8+ T cells." (PMID 39034411, 2024). "A study observed that the levels of CXCL1, CXCL2, CXCL5, CXCL7, and CXCL8 were higher in lung cancer compared to multiple other cancer types (breast, colorectal, esophageal, head and neck, and liver cancer)." (PMID 36612163, 2022). "Zhou et.al indicated that Schwann cells activated the PI3K/AKT/GSK-3β pathway and augmented the expression of Snail and Twist in lung cancer cells through CXCL5/CXCR2 axis, thus promoting the EMT and metastasis of lung cancer." (PMID 36522730, 2022). "PI3K/AKT pathway promotes EMT process of cancer which has been confirmed in many experiments 50-54, such as mouse adult Schwann cells-derived CXCL5 can activated PI3K/AKT pathway and through EMT-TFs (Snail, Twist) to promote EMT in lung cancer." (PMID 33976737, 2021). "Again, many of the immune-modulatory genes differentially expressed in the mouse model were site-specifically recapitulated, e.g., higher CCL2, CXCL5, CXCL9, CXCL11, CXCL14, CXCL17, and IDO1 in lung cancers and higher CXCL12, FGL1, and LAG3 in liver cancers." (PMID 33985562, 2021). "For lung lesion other than pulmonary inflammation, exposure to cigarette smoke, which leads to lung cancer and COPD, also induced CXCL5 expression in the lung." (PMID 33076408, 2020). "For lung cancer, high intra-tumoral concentrations of CXCR2 ligands (CXCL1, CXCL5, and CXCL8) and type 2 cytokines IL-4, IL-5, IL-10, and IL-13 have been reported for non-small cell lung cancer." (PMID 26231039, 2015). "A subsequent study in lung cancer has also demonstrated that DACH1 can suppress the secretion of CXCL5, thereby reducing CXCL5-mediated proliferation, migration and invasion." (PMID 26682253, 2015). "Besides, they blocked CXCL5 expression in SC significantly decreases the phosphorylation of AKT and GSK-3β in SC-treated lung cancer cells; PI3K inhibitor LY294002 blocks the activation of AKT/GSK-3β signaling in SC-conditioned lung cancer cells." (PMID 31921388, 2019). "For example, our previous study showed that C-X-C motif chemokine 5 (CXCL5) antibody synergistically enhanced the effect, without increasing the toxicity, of gefitinib, an epidermal growth factor receptor tyrosine kinase inhibitor, in treating lung cancer." (PMID 28672809, 2017). "Moreover, as with prostate cancer, a reverse relationship between DACH1 and CXCL5 was reported in tumor samples and low DACH1 correlated with reduced survival in lung cancer patients." (PMID 26682253, 2015). "Notably, CXCL5 KD did not affect the apoptosis of lung cancers without co-culture with CD8+ T cells." (PMID 39034411, 2024). "For example, Zhou at al. demonstrated that SCs conditioned by lung cancer cell secreted CXCL5 to activate PI3K/Akt/GSK-3β signaling and induced the expression of EMT regulators Snail and Twist in tumor cells, thereby aiding the spread and metastasis of lung cancer cells." (PMID 32308766, 2020).
gastric cancer (39 papers, 2010 to 2025). A primary or metastatic malignant neoplasm involving the stomach. "We also identified a specific chemokine, CXC motif chemokine ligand 5 (CXCL5), derived from TAMs to promote 5-FU-resistance of gastric cancer cells and further investigated the underlying molecular mechanism." (PMID 36151545, 2022). "In the present study, we investigated the role of CXCL5 in gastric cancer metastasis and explored the underlying mechanism." (PMID 32632106, 2020). "CXCL5 overexpression was also associated with late stage gastric cancer and high N stage, suggesting CXCL5 is involved in the progression of gastric cancer, especially in lymph node metastasis." (PMID 22950635, 2012). "In gastric cancer, CXCL5 is associated with late stages of the disease." (PMID 33458757, 2021). "The role and underlying mechanism of CXCL5 in gastric cancer (GC) metastasis remain unclear." (PMID 32632106, 2020). "In gastric cancer, MMP11+ mCAFs were primarily associated with COL11A+ CAFs, with a secondary association to CXCL5+ CAFs." (PMID 40552583, 2025). "CXCL5 can promote the metastasis of gastric cancer by inducing epithelial-mesenchymal transformation and activating neutrophils." (PMID 37274740, 2023). "In the present study, TAMs-derived CXCL5 was demonstrated to promote 5-FU-resistance and enhance the ability of anti-apoptosis of gastric cancer cells through the activation of PI3K/AKT/mTOR pathway, which has been shown to involve in cancer progression." (PMID 36151545, 2022). "M2-polarized macrophages inhibited apoptosis and increased 5-FU-resistance by activing the CXCL5/PI3K/AKT/mTOR pathway in gastric cancer cells." (PMID 36151545, 2022). "According to the literature, the increased secretion of ENA-78/CXCL5 in tumor tissues is associated with lymphatic metastases and tumor differentiation, with the induction of EMT, as exemplified by gastric cancer cells." (PMID 36354566, 2022). "Co-culturing M2-polarized macrophages in turn enhanced 5-FU-resistance of gastric cancer cells, and it was further verified that CXCL5 derived from M2-polarized macrophages promoted chemoresistance through activing the PI3K/AKT/mTOR pathway." (PMID 36151545, 2022). "The results denoted that the levels of CCL18 and CXCL5 in 5-FU-sensitive and 5-FU-resistant gastric cancer cells were below the detection limit of the assay and recorded as zero." (PMID 36151545, 2022). "Interaction between TAMs and gastric cancer cells promoted chemoresistance in gastric cancer via CXCL5/PI3K/AKT/mTOR pathway." (PMID 36151545, 2022). "To investigate the clinical relevance of CXCL5 in prognosis of patients with gastric cancer, we detected the expression level of CXCL5 in clinical samples from 103 patients by immunohistochemistry." (PMID 36151545, 2022). "Based on the results, we focused on CXCL5 in the further studies to verify its role in 5-FU-resistance of gastric cancer cells." (PMID 36151545, 2022). "CXCL5 derived from TAMs in gastric cancer promotes metastasis by activating the CXCR2/STAT3 feed-forward loop." (PMID 35853880, 2022). "A constructed miRNA-mRNA network showed that CXCL5, CXCL9, and CXCL10 are target genes of miR-588, and high expression of miR-588, CXCL5, CXCL9, and CXCL10 is associated with the prolonged survival in gastric cancer patients." (PMID 34283058, 2021). "Taken together, these findings suggest that CXCL5 enhances the migration and invasion abilities of gastric cancer cells through the induction of EMT." (PMID 32632106, 2020). "To further determine the effects of CXCL5-activated neutrophils on gastric cancer metastasis, we established a peritoneal metastasis model in nude mice." (PMID 32632106, 2020). "To investigate the role of CXCL5 in gastric cancer, we first examined the expression of CXCL5 in a total of 66 paired gastric tumor tissues and adjacent non-tumor tissues and four human GC cell lines." (PMID 32632106, 2020).
gastric cancer (continued). "We showed that gastric cancer-derived CXCL5 activated neutrophils to promote GC metastasis, which implies a close link between CXCL5 and neutrophils in gastric cancer." (PMID 32632106, 2020). "CXCL5 levels were found to be higher in late stage gastric cancer patients compared to levels in patients with benign conditions." (PMID 21092330, 2010). "Additionally, macrophages serve as major sources of CXCL1 and CXCL5 in the gastric cancer microenvironment, and promote the migration of gastric cancer cells by activating a CXCR2/STAT3 feed-forward loop." (PMID 41583453, 2025). "Chemokines CXCL1 and CXCL5 in macrophages are critical in gastric cancer metastasis." (PMID 38887558, 2024). "By analyzing the co-expression correlation between CPT1A, IL-8, CXCL5, STC1 and CD44 in stomach cancer tissues through TCGA database, we found that these genes except CXCL5 were positively correlated with CD44 and were positively associated with at least one MSC markers (ENG, THY1, NT5E)." (PMID 37158903, 2023). "Moreover, the staining data confirmed the correlation between the expression of CXCL5 and the density of M2-polarized macrophages, and patients with high expression of CXCL5 in gastric cancer lesions had low overall survival rates." (PMID 36151545, 2022). "As indicated by CCK-8 assay, co-culturing MR macrophages or addition of rhCXCL5 could induce 5-FU-resistance, whereas CXCL5 neutralizing antibody decreased MR macrophages-mediated resistance to 5-FU in gastric cancer cells." (PMID 36151545, 2022). "Based on the data above, we speculated that gastric cancer cells, especially chemoresistant cells could induce macrophages polarization to M2 phenotype, which lead to the increased secretion of CXCL5." (PMID 36151545, 2022). "CXCL5 promotes the migration and invasion of gastric cancer cells by inducing the tumor EMT." (PMID 36290882, 2022). "It was revealed that co-culturing MR macrophages or rhCXCL5 could both reduce apoptotic proportion, however, applying CXCL5 neutralizing antibody decreased MR macrophages-mediated resistance to apoptosis in gastric cancer cells." (PMID 36151545, 2022). "5-FU-sensitive gastric cancer cells were cultured alone or co-cultured with MR macrophages with the presence of rhCXCL5 (10 ng/ml) or CXCL5 neutralizing antibody (0.5 μg/ml) for 48 h followed by being treated with 15 μg/ml 5-FU for 24 h, then the rates of apoptosis were analyzed." (PMID 36151545, 2022). "CXCL5 promoted gastric cancer metastasis by activating neutrophils." (PMID 35504887, 2022). "Some researchers have found that LBX2-AS1 could promote cell proliferation, migration and invasion through Mir-4766-5P mediated CXCL5 upregulation in gastric cancer." (PMID 36313642, 2022). "High level of CXCL5 could in turn recruit monocytes to form more M2-polarized macrophages and further promote the development of chemoresistant microenvironment in gastric cancer." (PMID 36151545, 2022). "CXCL5 directly enhances tumor cell survival and proliferation in gastric cancer." (PMID 34194499, 2021). "Expression of CXCL5/9/10 in gastric cancer and normal tissue samples." (PMID 33323542, 2020). "Our study suggests that CXCL5 is a potential target for the treatment of gastric cancer metastasis." (PMID 32632106, 2020). "Based on these studies, we hypothesized that CXCL5 may exert dual roles in both cancer cells and microenvironmental cells such as neutrophils, finally accelerating gastric cancer progression." (PMID 32632106, 2020). "Similarly, CXCL5 activated neutrophils to improve the metastatic ability of gastric cancer cells." (PMID 37569554, 2023). "Clinically, high expression of CXCL5 in gastric cancer samples was associated with the high infiltration of CD163 positive macrophages and CD206 positive macrophages, and patients with high expression of CXCL5 presented lower overall survival (OS) rates than those with low expression of CXCL5." (PMID 36151545, 2022).
gastric cancer (continued). "Neutrophils in the stroma of gastric cancer (GC) produce IL17a and CXCL5 both promoting EMT, indicated by upregulation of VIM and ZEB1, whereas CDH1 is repressed." (PMID 34459003, 2021). "CXCL5 induced EMT in GC cells via regulation of ERK/Snail pathway and pro-tumor activation of neutrophils, which cooperatively promoted gastric cancer metastasis." (PMID 32632106, 2020). "Our findings suggest that CXCL5 exerts tumor-promoting roles in gastric cancer by acting on both cancer cells and neutrophils, suggesting that it may serve as a potential target for gastric cancer therapy." (PMID 32632106, 2020). "M2 TAMs in the TME were found to inhibit apoptosis and promote resistance to 5-fluorouracil (5-FU) by secreting CXC chemokine ligand 5 (CXCL5) and activating the PI3K/AKT/mTOR signaling pathway in gastric cancer cells." (PMID 39889181, 2025). "In gastric cancer, macrophage-derived CXCL5 promotes tumor cell migration through the CXCR2/STAT3 pathway and facilitates chemoresistance via the CXCL5/PI3K/AKT/mTOR pathway." (PMID 38642131, 2024). "Moreover, CXCL5 activated neutrophils could promote gastric cancer metastasis in vivo." (PMID 32632106, 2020). "The results of western blot showed a similar change trend in the expression of EMT markers as that observed for rhCXCL5 treatment, which indicates that CXCL5 in gastric cancer microenvironment could induce EMT in GC cells." (PMID 32632106, 2020). "To test whether CXCL5 promotes gastric cancer cell migration and invasion by inducing EMT, we detected the expression of EMT markers in CXCL5-treated GC cells." (PMID 32632106, 2020). "Gastric cancer cells secrete TNF-α to induce macrophages to release CXCL1 and CXCL5." (PMID 41583453, 2025). "The pro-metastatic role of TANs via lymphangiogenesis is nevertheless observed in multiple cancers—gastric cancer (CD15+ TANs correlate with nodal metastasis), bladder cancer (circDHTKD1/CXCL5/VEGFC axis; ETV4-CXCL1/8-MMP9/VEGFA axis), and now LUAD (CCL15-CCR1-VEGFC)." (PMID 40739091, 2025). "Gastric cancer cells secrete TNF-α to induce release of CXCL1 and CXCL5 from macrophages." (PMID 41583453, 2025). "For instance, LBX2-AS1 is up-regulated in gastric cancer and silencing LBX2-AS1 restrains proliferative, migratory, and invasive capacities of gastric cancer cells by miR-491-5p/ZNF703, miR-219a-2-3p/FUS or miR-4766-5p/CXCL5 axis." (PMID 34552959, 2021). "Additionally macrophages are also the major sources of chemokines and chemokine receptors in the gastric cancer microenvironment, such as CXCL1 and CXCL5, and promote migration through activating the CXCR2/STAT3 feed-forward circuit." (PMID 33112406, 2020). "Using a robust proteomic approach, we identified numerous molecules secreted into the omental tissue conditioned medium (CM) which may promote gastric cancer cellular aggressiveness (i.e., IL-6, IL-8, MMP9, FN1, and CXCL-5)." (PMID 31803630, 2019). "Unlike CXCL4, the level of CXCL5 is greatly enhanced in serum in the late stages of gastric cancer." (PMID 36612163, 2022). "CXCL5 could recruit monocytes to form more M2-polarized macrophages and further promote the development of chemoresistance through the activation of PI3K/AKT/mTOR pathway in gastric cancer." (PMID 36151545, 2022). "Taken together, our results indicate that CXCL5 acts on gastric cancer cells to induce EMT and mediates pro-tumor activation of neutrophils, which synergistically promotes the metastatic ability of GC cells." (PMID 32632106, 2020).